RNU6-281P (RNA, U6 small nuclear 281, pseudogene)
Gene: Small nuclear RNA gene on chromosome 3 (70,808,350 to 70,808,452, forward strand). Ensembl gene ENSG00000206939.
Homologues: Orthologues: chimpanzee U6 (100% identical), macaque U6 (94% identical), dog U6 (79% identical). Paralogues in human: RNU6-1263P (88% identical), RNU6-15P (88% identical), RNU6-1122P (87% identical), RNU6-33P (87% identical), RNU6-1 (86% identical), RNU6-1011P (86% identical), RNU6-1060P (86% identical), RNU6-116P (86% identical), RNU6-2 (86% identical), RNU6-3P (86% identical), RNU6-463P (86% identical), RNU6-476P (86% identical), and 1289 more.